PRMT5 (protein arginine methyltransferase 5)
Diseases named in the same sentence as PRMT5 in open-access papers (continued):
Sharing a sentence is not in itself a finding about the gene and the disease.
Pancytopenia (3 papers, 2018 to 2025). An abnormal reduction in numbers of all blood cell types (red blood cells, white blood cells, and platelets). "Studies have shown that absence of Prmt5 in mice almost completely eliminates symmetrically di-methylated arginine modification leading to fatal pancytopenia, especially loss of Prmt5 impairs erythroid differentiation with an reduced CD71/Ter119 double-positive cells in the BM and spleen." (PMID 40214280, 2025).
squamous cell carcinoma (3 papers, 2013 to 2024). A carcinoma arising from squamous epithelial cells. "Protein arginine methyltransferase 5 (PRMT5) is known to be oncogenic in many cancers, including squamous cell carcinoma (SCC)." (PMID 39594744, 2024). "In summary, this study highlights that PRMT5 is overexpressed in squamous cell carcinoma (SCC) and correlates with poor patient survival." (PMID 39594744, 2024). "However, the role of PRMT5 in squamous cell carcinoma (SCC) remains largely unexplored." (PMID 39594744, 2024).
Thrombocytopenia (3 papers, 2025). A reduction in the number of circulating thrombocytes. "Thrombocytopenia is a known on-target dose-limiting toxicity for the first generation of SAM competitive or SAM cooperative PRMT5 inhibitors that entered clinical development." (PMID 40377999, 2025).
acute leukemia (2 papers, 2020 to 2025). A clonal (malignant) hematopoietic disorder with an acute onset, affecting the bone marrow and the peripheral blood. "However, the importance of splicing modulation after PRMT5 inhibition is suggested by the fact that PRMT5 inhibitors kill more efficiently SRSF2P95H-mutated cells than SRSF2WT control cells in a model of acute leukemia due to MLL-AF9 gene fusion." (PMID 32784800, 2020).
acute myocardial infarction (2 papers, 2019 to 2020). Necrosis of the myocardium, as a result of interruption of the blood supply to the area. "The purpose of this research is to determine whether the expression levels of the PRMT5 gene in peripheral blood can be used as a biomarker for predicting the risk of Acute Myocardial Infarction (AMI)." (PMID 30704408, 2019). "People with shrinking expression level of PRMT5 in peripheral blood are prone to developing stable coronary artery disease and acute myocardial infarction, suggesting that PRMT5 might play a critical role in cardiovascular diseases." (PMID 33424610, 2020).
acute promyelocytic leukemia (2 papers, 2022 to 2026). An aggressive form of acute myeloid leukemia (AML), characterized by arrest of leukocyte differentiation at the promyelocyte stage, due to a specific chromosomal translocation t(15;17) in myeloid cells. "In Acute Promyelocytic Leukemia (APL), PRMT5 contributes to resistance against arsenic trioxide treatment via another non‐histone related mechanism." (PMID 40181550, 2026). "PRMT5 is also highly expressed in acute promyelocytic leukemia (APL), an AML subtype mainly driven by the PML-RARα oncoprotein." (PMID 36358861, 2022).
adenoid cystic carcinoma (2 papers, 2025). A malignant tumor arising from the epithelial cells. "Similarly, single-cell RNA sequencing of adenoid cystic carcinoma organoids revealed PRMT5 upregulation correlated with MYB/MYC genes—a finding that not only uncovered novel biomarkers but also validated PRMT5 inhibitors as a viable therapeutic strategy currently in phase I clinical trials." (PMID 41425705, 2025).
anaplastic large cell lymphoma (2 papers, 2020 to 2023). Anaplastic large cell lymphoma (ALCL) is a rare and aggressive peripheral T-cell non-Hodgkin lymphoma, belonging to the group of CD30-positive lymphoproliferative disorders, which affects lymph nodes and extranodal sites. "While literature strongly supports a requisite role for PRMT5 in the context of large cell lymphomas, emerging evidence now suggests aberrant PRMT5 expression additionally disrupts critical regulatory mechanisms and contributes to tumor progression in CLL28." (PMID 36609611, 2023).
brain cancer (2 papers, 2023). A primary or metastatic malignant neoplasm affecting the brain. "Interestingly, PRMT5 is also associated with enriched AS of genes in DDR pathways in blood and brain cancers, suggesting PRMT5 may act as a major regulator of DDR genes through several layers of mechanism." (PMID 37861290, 2023). "This is consistent with the role of PRMT5 in the regulation of pre-mRNA splicing and the enrichment of DDR-related splicing in blood and brain cancers." (PMID 37861290, 2023).
breast invasive carcinoma (2 papers, 2019 to 2021). "Moreover, PRMT5 and FOXP1 expression profile in invasive breast cancer patients undergo neoadjuvant chemotherapy." (PMID 34124017, 2021).
chronic heart failure (2 papers, 2024 to 2025). "Our experimental findings also propose that PRMT5 is a novel molecular target for the pharmacological therapy of chronic heart failure." (PMID 40619438, 2025). "Although further studies, especially in the form of clinical trials, are needed to clarify the safety and optimize the administration schedule of PRMT5 inhibitors, the present study indicates that therapeutic strategies targeting PRMT5 are of considerable interest for chronic heart failure therapy." (PMID 38503742, 2024).
clear cell sarcoma (2 papers, 2022 to 2024). A rare malignant neoplasm with melanocytic differentiation characterized by the presence of polygonal or spindle shaped clear cells. "The fusion protein EWSR1–ATF1 interacts with protein arginine methyltransferase 5 (PRMT5), thereby augmenting gene transcription for the maintenance of cell proliferation in clear cell sarcoma of soft tissue cells." (PMID 39156764, 2024).
coronary artery disease (2 papers, 2020 to 2021). "Notably, in the peripheral blood obtained from 178 patients with acute myocardial infarction (AMI) and stable coronary artery disease (CAD), PRMT5 was significantly lower in AMI patients compared to stable CAD patients." (PMID 34685445, 2021).
cutaneous melanoma (2 papers, 2013 to 2024). A primary melanoma arising from atypical melanocytes in the skin. "Furthermore, nuclear PRMT5 was significantly decreased in metastatic melanomas as compared to primary cutaneous melanomas." (PMID 24098663, 2013).
endometriosis (2 papers, 2022 to 2025). The growth of functional endometrial tissue in anatomic sites outside the uterine body. "We next determined PRMT5 mRNA expression in the mid-secretory phase eutopic endometrium of endometriosis patients." (PMID 36195592, 2022). "Transcriptome analysis showed that decreased PRMT5 activity led to NF-κB signaling activation by inducing p65 translocation to the nucleus, which was also observed in endometriosis patients." (PMID 36195592, 2022). "Western blot data further confirmed the decreased level of eutopic endometrial PRMT5 in endometriosis patients." (PMID 36195592, 2022). "Here, we found that PRMT5 expression was decreased in the mid-secretory endometrium of endometriosis patients, predominantly in stromal cells." (PMID 36195592, 2022). "Our data confirmed that the expression of PRMT5 was suppressed in the eutopic mid-secretory endometrium of endometriosis patients, especially in stromal cells." (PMID 36195592, 2022). "Due to the potential regulatory effect of PRMT5 on decidualization, we speculated that overexpression of PRMT5 may improve the decidualization of endometrial stromal cells from endometriosis patients." (PMID 36195592, 2022). "Furthermore, we confirmed that overexpression of PRMT5 rescued the decidualization defect of primary hEnSCs from endometriosis patients." (PMID 36195592, 2022). "Inhibition of PRMT5 activity impaired human endometrial stromal cell decidualization partly by activating the NF-kappa B (NF-κB) signaling pathway, while overexpression of PRMT5 rescued the decidualization defect in endometrial stromal cells from endometriosis patients." (PMID 36195592, 2022). "In addition, p65 nuclear translocation and increased expression of NF-κB signaling-related inflammatory factors were also observed in primary hEnSCs from endometriosis patients with reduced expression levels of PRMT5." (PMID 36195592, 2022). "Here, we observed that the expression level of PRMT5, the main type II PRMT, was decreased in the endometrium of endometriosis patients, predominantly in stromal cells." (PMID 36195592, 2022). "Immunohistochemical staining (IHC) analysis revealed that the reduction in PRMT5 expression in the eutopic endometrium of endometriosis patients was observed mainly in stromal cells but not in epithelial cells." (PMID 36195592, 2022). "Finally, overexpression of PRMT5 rescued the defective expression of IGFBP1 and prolactin in primary endometrial stromal cells from endometriosis patients." (PMID 36195592, 2022). "Notably, PRMT5 overexpression restores IGFBP1 and PRL expression in eutopic ESCs of endometriosis patients, suggesting that PRMT5 dysregulation contributes to impaired decidualization in endometriosis." (PMID 40072055, 2025). "However, PRMT5 supplementation obviously promoted IGFBP1 mRNA expression (31.56 vs. 91.18, P < 0.05) and secreted PRL levels (85.17 vs. 115.33 ng/mL, P < 0.001), indicating that PRMT5 rescued the decidualization defect of endometrial stromal cells from endometriosis patients." (PMID 36195592, 2022). "Our qPCR showed that the expression level of PRMT5, but not PRMT1 or PRMT3, was obviously decreased in the eutopic endometrium of endometriosis patients compared with that in fertile controls." (PMID 36195592, 2022).
female infertility (2 papers, 2021). Diminished or absent ability of a female to achieve conception. "Previous studies have demonstrated that PRMT5 is required for germ cell development, as the loss of Prmt5 in primordial germ cells (PGCs) causes male and female sterility." (PMID 34113620, 2021). "Loss of Prmt5 in granulosa cells caused aberrant follicle development and female infertility." (PMID 34448450, 2021). "Inactivation of Prmt5 in granulosa cells resulted in aberrant follicle development and female infertility." (PMID 34448450, 2021).
gastric tumor (2 papers, 2015 to 2022). "We propose that as opposed to the tumor-promoting role of PRMT5 well-established in the progression of various cancer types, PRMT5 functions as a tumor suppressor in vivo, at least during gastric tumor formation." (PMID 35864961, 2022). "As expected, the invasive cells in submucosa layer were tdTomato-positive, demonstrating that Prmt5 mutant cells contributed to the occurrence and the progression of gastric tumors." (PMID 35864961, 2022). "Unexpectedly, all Prmt5 mutants developed spontaneous gastric tumor at antrum within 4 months of age, accompanied by the hyperactivation of Wnt/β-catenin signaling." (PMID 35864961, 2022).
heart failure (2 papers, 2024 to 2025). Inability of the heart to pump blood at an adequate rate to meet tissue metabolic requirements. "As we found that Prmt5 deficiency in fibroblasts suppressed cardiac dysfunction, we hypothesized that PRMT5 inhibitors have anti-heart failure effects via their inhibition of cardiac fibrosis." (PMID 38503742, 2024). "The objective of this study was to elucidate the function and mechanism of action of PRMT5 in cardiomyocytes using a cell culture study and an animal model of heart failure induced by pressure overload." (PMID 40619438, 2025). "Consistent with the results that cardiac function was reduced by PRMT5 overexpression, the lung weight to body weight ratio was significantly augmented, suggesting that PRMT5-TG mice had accelerated heart failure compared with WT mice." (PMID 40619438, 2025). "To investigate the functional role of the Prmt5 gene in the development of heart failure, we generated fibroblast-specific PRMT5-KO mice." (PMID 38503742, 2024). "We examined the pharmacological effect of a PRMT5 inhibitor on a mouse model of pressure overload-induced heart failure." (PMID 38503742, 2024). "In addition to these therapeutic candidates, our findings in this study propose the potential of PRMT5 as a novel therapeutic target in heart failure." (PMID 40619438, 2025). "However, the role of PRMT5 in cardiac fibrosis during the development of heart failure is still unknown." (PMID 38503742, 2024). "Although further investigation is required to determine whether crosstalk between H4R3 di-methylation and histone acetylation affects heart failure development, our data suggest that histone methylation by PRMT5 may not be the primary driver of PRMT5-induced hypertrophy." (PMID 40619438, 2025).
Huntington disease (2 papers, 2018 to 2021). Huntington disease (HD) is a rare neurodegenerative disorder of the central nervous system characterized by unwanted choreatic movements, behavioral and psychiatric disturbances and dementia. "In addition, the importance of PRMT5 in preventing Huntington’s disease (HD) has been suggested." (PMID 34685445, 2021).
interstitial lung disease (2 papers, 2024 to 2025). A diverse group of lung diseases that affect the lung parenchyma. "Furthermore, the presence of anti-PRMT5 antibodies is associated with the progression of interstitial lung disease (ILD), particularly fibrosing ILD." (PMID 40790333, 2025). "Furthermore, elevated levels of anti-PRMT5 antibodies were significantly associated with the presence of interstitial lung disease (ILD) (p < 0.0001) and antinuclear antibody positivity (p < 0.01)." (PMID 40790333, 2025). "Patients with SSc who fulfilled the criteria of progressive fibrosing interstitial lung disease (ILD) (PF-ILD) in the subsequent 24-month follow-up demonstrated significantly increased basal levels of anti-PRMT5 antibodies compared with the patients with SSc without developing PF-ILD." (PMID 38684324, 2024).
ischemia (2 papers, 2022 to 2024). A hypoperfusion of the BLOOD through an organ or tissue caused by a PATHOLOGIC CONSTRICTION or obstruction of its BLOOD VESSELS, or an absence of BLOOD CIRCULATION. "Together, these results suggest that Prmt5 KO in ECs attenuates ischemia-induced angiogenesis and injury-induced muscle regeneration." (PMID 35531958, 2022). "Endothelial-specific Prmt5-KO mice were generated to define the role of PRMT5 in hindlimb ischemia–induced angiogenesis." (PMID 35531958, 2022). "Therefore, the regulation of PRMT5 on SHH signaling may be one of the important mechanisms of its ischemia protection." (PMID 38372724, 2024).
lung small cell carcinoma (2 papers, 2019 to 2022). "Many target genes are involved in PRMT5-induced lung small cell carcinoma." (PMID 36364261, 2022).
lymphocytic leukemia (2 papers, 2015 to 2023). "In addition to upregulation in solid tumor and hematological malignancies, we previously found that PRMT5 is dysregulated in HTLV-1-transformed T-cells, lymphocytic leukemia T-cell lines, and ATL patient PBMCs." (PMID 36819050, 2023).
lymphopenia (2 papers, 2020 to 2023). Reduction in the number of lymphocytes. "Similar to our study, the investigators generated a T-cell-specific PRMT5 conditional knockout mouse (CD4Cre PRMT5fl/Δ mice), which showed loss of iNKT cells in the thymus and T cell lymphopenia in the periphery." (PMID 32328070, 2020). "In addition, T cell‐specific deletion of PRMT5 leads to peripheral T cell lymphopenia." (PMID 36946061, 2023).
malignant glioma (2 papers, 2020 to 2021). A grade III or grade IV glioma arising from the central nervous system. "CLNS1A knockdown increased sensitivity to PRMT5 inhibitor EPZ015666 in malignant glioma, which may due to the reducing of splicing capacity." (PMID 32373523, 2020).
metastatic melanoma (2 papers, 2013 to 2024). A melanoma that has spread from its primary site to another anatomic site. "In human metastatic melanoma cell lines, PRMT5 was predominantly cytoplasmic, and associated with its enzymatic cofactor Mep50, but not STAT3 or cyclin D1." (PMID 24098663, 2013). "In human metastatic melanoma cell lines, PRMT5 was predominantly cytoplasmic, and associated with its cofactor Mep50." (PMID 24098663, 2013). "In patient specimens, PRMT5 was upregulated in melanocytic nevi, malignant, and metastatic melanoma, compared to normal epidermis." (PMID 24098663, 2013). "In this report, we demonstrate for the first time that PRMT5 is upregulated in primary human malignant and metastatic melanoma specimens, as well as in melanocytic nevi." (PMID 24098663, 2013). "PRMT5 protein was significantly increased in both cytoplasmic and nuclear compartments of malignant and metastatic melanomas, as well as in melanocytic nevi." (PMID 24098663, 2013).
microcephaly (2 papers, 2023 to 2024). A congenital or acquired developmental disorder in which the circumference of the head is smaller than normal for the person's age and sex. "Altogether, PRMT5 deficiency in NPCs leads to a severe microcephaly phenotype, suggesting that PRMT5 plays a critical role in cortical development." (PMID 38459149, 2024).
multiple endocrine neoplasia type 1 (2 papers, 2015 to 2020). An autosomal dominant tumor predisposition syndrome caused by pathogenic variants in the MEN1 gene, characterized by an increased risk of tumors of the parathyroid glands, pituitary gland, and foregut neuroendocrine tumors (most commonly pancreatic islet cells). "Menin, the gene mutated in multiple endocrine neoplasia type 1, recruits the protein arginine methyltransferase 5 (PRMT5) to growth arrest-specific 1 (Gas1) promoter." (PMID 25660620, 2015).
myelodysplastic syndrome (2 papers, 2021). A clonal hematopoietic disorder characterized by dysplasia and ineffective hematopoiesis in one or more of the hematopoietic cell lines. "The remaining trials are evaluating the safety and efficacy of PRMT5 inhibition are in patients with advanced/metastatic solid tumors (Drug: PF-06939999; NCT03854227), Myelodysplastic Syndrome (MDS) and AML (Drug: GSK3326595; NCT03614728), and NHL/MDS (Drug: JNJ64619178; NCT03573310)." (PMID 33440687, 2021).
myeloid malignancies (2 papers, 2025 to 2026). "While various PRMT5 inhibitors are currently under clinical investigation in various oncologic indications, two drugs were also assessed in early clinical trials on patients with myeloid malignancies." (PMID 40374809, 2025). "Ongoing research into PRMT5 inhibitors may provide novel strategies to counteract its oncogenic effects, offering new avenues for targeted therapies in AML, CML, and other myeloid neoplasms." (PMID 40374809, 2025).
Obesity (2 papers, 2025). Accumulation of substantial excess body fat. "Interestingly, PRMT5 also regulates lipid metabolism in people, and negative associations between PRMT5 and dogs and people with obesity have been observed." (PMID 40123416, 2025). "However, the m6A demethylase, often referred to as “erasers”, comprises the alpha-ketoglutarate-dependent dioxygenase alkB homolog 1-8 (ALKBH1-8), fat mass and obesity-related proteins (FTO), and protein arginine methyltransferase 5 (PRMT5)." (PMID 40958857, 2025).
oral cancer (2 papers, 2023 to 2024). "Interestingly, PRMT1-silenced cells did not change the protein levels of FXR1 or FXR2, indicating that FXR1 may be a direct substrate of PRMT5 in oral cancer cells." (PMID 38709899, 2024). "We speculate that these cells gain growth and survival advantage against IR treatment to affect the outcome of the radiotherapy significantly, as high expression levels of PRMT5 and APE1 have been associated with poor outcomes of radiation therapy in oral cancer patients." (PMID 37887269, 2023).